VCAN (versican)
Diseases named in the same sentence as VCAN in open-access papers (continued):
Sharing a sentence is not in itself a finding about the gene and the disease.
abdominal aortic aneurysm (2 papers, 2018 to 2022). Enlargement and ballooning of the vessel that supplies arterial blood to the abdomen, pelvis and legs. "In contrast, abdominal aortic aneurysms (AAA) appear to have decreased versican concentration and mRNA levels." (PMID 36012466, 2022).
adenoma (2 papers, 2017 to 2021). A neoplasm arising from the epithelium. "Versican, a large extracellular matrix proteoglycan that regulates many malignant biological processes, was highly expressed in the stroma of high-risk adenomas and carcinomas compared with low-risk adenomas." (PMID 34880916, 2021). "In the present study we investigated lumican and versican protein expression in adenoma-to-carcinoma progression and their potential association with commonly occurring genomic alterations involved in that process." (PMID 28481899, 2017). "The aim of this study was to characterize versican and lumican protein expression in tumor progression and investigate their association with CNAs commonly associated with adenoma-to-carcinoma progression." (PMID 28481899, 2017). "For versican staining the same analyses were performed, with results for 15 high-risk adenomas and 48 MSS carcinomas." (PMID 28481899, 2017). "We did find indications, however, that stromal expression of versican in high-risk adenomas and CRCs was associated with gain of chromosome 13q." (PMID 28481899, 2017). "In conclusion, in the present study protein expression of both lumican and versican was upregulated in high-risk adenomas and carcinomas compared to low-risk adenomas, indicating that they may play a role in adenoma-to-carcinoma progression." (PMID 28481899, 2017). "In the current study, versican was increased in the tumor stroma of high-risk adenomas and carcinomas compared to low-risk adenomas, suggesting that versican plays a role in remodeling of tumor stroma in adenoma-to-carcinoma progression." (PMID 28481899, 2017). "There was a trend for versican expression in tumor stroma to be more prevalent in high-risk adenomas compared to low-risk adenomas (67% versus 36%; P = 0.07, data not shown)." (PMID 28481899, 2017). "Neither versican expression in the epithelium nor in the stroma was significantly different between adenomas and carcinomas." (PMID 28481899, 2017). "The chromosomal regions of the LUM and VCAN genes (12q21.3-q22 and 5q14.3, respectively) are not among the most commonly gained regions in adenoma-to-carcinoma progression." (PMID 28481899, 2017). "Although previous work revealed higher mRNA expression levels of the LUM and VCAN genes in carcinomas compared to adenomas, we did not observe significant correlations between mRNA and protein levels." (PMID 28481899, 2017).
Alzheimer disease (2 papers, 2018 to 2021). A progressive, neurodegenerative disease characterized by loss of function and death of nerve cells in several areas of the brain leading to loss of cognitive function such as memory and language. "Versican was shown to increase expression in humans during progression of Alzheimer’s disease." (PMID 30333727, 2018).
cardiomyopathies (2 papers, 2023 to 2024). "To assess the translational relevance of our findings, we examined the production and localization of versican in cardiac tissue from patients with cardiomyopathies." (PMID 38076279, 2023). "In patients with cardiomyopathies, elevated expression and accumulation of versican and the DPEAAE fragment were observed in fibrotic regions of the myocardium." (PMID 38076279, 2023). "In this study, we have examined the spatial distribution and temporal expression of versican during cardiac fibrosis development following pressure overload in mice and in patients with cardiomyopathies." (PMID 38076279, 2023). "As in mice with aortic banding, we found that V0 and V1 isoforms of versican were upregulated in patients with cardiomyopathies." (PMID 38076279, 2023). "Notably, in patients with cardiomyopathy, versican protein levels extended from the perivascular region into the tissue interstitium." (PMID 39199356, 2024). "Thus, combining our findings from pressure overload in mice and myocardial samples from cardiomyopathy patients indicates that versican and the DPEAAE fragment are involved in different phases of cardiac fibrosis development." (PMID 38076279, 2023). "•Cardiomyopathy patients have accumulation of versican and DPEAAE in fibrotic areas." (PMID 38076279, 2023).
cerebrovascular disease (2 papers, 2021). "Genetic variants in VCAN are associated with cerebrovascular disease and dementia." (PMID 34720873, 2021). "We found that genes related to cerebrovascular diseases, such as COL4A1, COL4A2, VCAN and APOE were significantly enriched in the cerebrovascular ECM network." (PMID 33730931, 2021).
colitis (2 papers, 2023 to 2024). Inflammation of the colon. "One previous study has reported that increased cleavage of versican worsened colitis in the gut, compared to animals with less versican cleavage." (PMID 38076279, 2023). "A recent study demonstrated that VCAN accumulation and low VKINE expression ameliorate acute colitis." (PMID 39682243, 2024).
colon adenocarcinoma (2 papers, 2007 to 2017). "Another report showed a dramatic increase of decorin and versican in colon adenocarcinoma, which constitute the vast majority of the CS/DS-proteoglycans, and a deep altered chain composition and length." (PMID 28827814, 2017). "A significant correlation between tumor grade and degree of versican expression has also been observed in canine colonic adenocarcinomas." (PMID 17662123, 2007).
colorectal tumor (2 papers, 2019 to 2024). "However, combined inhibition of the ECM genes, VCAN, and ERK signaling may be more effective for preventing OSBPL2 loss induced colorectal tumor growth." (PMID 38267463, 2024). "OSBPL2 was negatively correlated with VCAN, AREG, and EREG, whereas there was a positive correlation between VCAN, AREG, and EREG in colorectal tumors." (PMID 38267463, 2024).
developmental delay (2 papers, 2013 to 2023). "For example, mutations in Slc38a3 cause overall developmental delay, intellectual disability, hypotonia, and loss of speech, Adamts5 prevents impaired cardiac function by regulating versican degradation, and Cdkn2a/b locus influences the risk of diabetes through both islet and non-islet mechanisms." (PMID 37305038, 2023). "Normal notch1B and tie2 expression suggest that the failure of bmp4 and versican to become AV canal-restricted was not merely due to developmental delay, nor to an overall mispatterning of AV boundaries." (PMID 24311987, 2013).
Duchenne muscular dystrophy (2 papers, 2020 to 2024). Duchenne muscular dystrophy (DMD) is a neuromuscular disease characterized by rapidly progressive muscle weakness and wasting due to degeneration of skeletal, smooth and cardiac muscle. "There is a persistent, aberrant accumulation of V0/V1 versican in skeletal muscles from patients with Duchenne muscular dystrophy and in diaphragm muscles from mdx mice." (PMID 32632164, 2020).
endometriosis (2 papers, 2018 to 2024). The growth of functional endometrial tissue in anatomic sites outside the uterine body. "No relevant difference was seen within hormonal medication use or types of endometriosis, making VCAN a universal biomarker to use as a target for visualization of endometrial stroma." (PMID 39373851, 2024). "For both MMP11 and VCAN, staining was observed in adjacent tissue (MMP11: vessel walls, VCAN: smooth muscle cells, loose connective tissue, vessel walls), however significant less than in endometriosis, resulting in high TIS differences." (PMID 39373851, 2024). "VCAN resulted in a high TASC score due to gene upregulation in both peritoneal and deep endometriosis, its association with fibrosis and low RNA expression in surrounding tissue." (PMID 39373851, 2024). "MMP11 and VCAN showed the largest upregulation in endometriosis compared to adjacent tissue and showed a membranous or extracellular staining pattern." (PMID 39373851, 2024). "Further, little is known regarding the correlation between VCAN and endometriosis." (PMID 39373851, 2024). "Immunohistochemical evaluation of ten potential biomarkers to use as a target in fluorescence guided surgery in endometriosis surgery showed MMP11 and VCAN to be the most promising biomarkers." (PMID 39373851, 2024).
esophageal cancer (2 papers, 2021 to 2022). A primary or metastatic malignant neoplasm involving the esophagus. "High levels of ANGPT2, FOS, and MS4A4A were correlated with poor prognosis of esophageal cancer, while high level of VCAN was correlated with better prognosis of esophageal cancer." (PMID 36569220, 2022). "High levels of ANGPT2, FOS, and MS4A4A were correlated with poor prognosis of esophageal cancer, while high levels of VCAN were correlated with better prognosis of esophageal cancer." (PMID 36569220, 2022). "In this study, we found that VCAN is related to a better prognosis of esophageal cancer, either." (PMID 36569220, 2022). "We found that compared with normal human esophageal tissues, ANGPT2, VCAN, and FOS were significantly upregulated in esophageal cancer tissues, MS4A4A was significantly downregulated in esophageal cancer." (PMID 36569220, 2022). "In the total 182 hub genes, four hub genes including ANGPT2, VCAN, MS4A4A, and FOS had significant prognostic value in esophageal cancer." (PMID 36569220, 2022). "In the prognostic model construction of esophageal cancer, multifactor Cox analysis showed that M stage, N stage, VCAN, and MS4A4A were significant predictive factors of esophageal cancer and the model prediction efficiency was moderate accurate." (PMID 36569220, 2022). "Among 182 genes, four genes including ANGPT2, VCAN, MS4A4A, and FOS had significant prognostic value in esophageal cancer." (PMID 36569220, 2022). "Four genes including ANGPT2, VCAN, MS4A4A, and FOS were considered to have significant prognostic value in esophageal cancer." (PMID 36569220, 2022). "Thus, we considered that hub genes including ANGPT2, VCAN, MS4A4A, and FOS were involved in the pathogenesis of esophageal cancer." (PMID 36569220, 2022). "Thus, VCAN and MS4A4A also participated the effect of neutrophils in esophageal cancer." (PMID 36569220, 2022). "Next, we analyzed the expression of these four important genes (VCAN, ANGPT2, MS4A4A, and FOS) between esophageal cancer and normal esophageal tissues." (PMID 36569220, 2022).
fibrosarcoma (2 papers, 2017). A malignant mesenchymal fibroblastic neoplasm affecting the soft tissue and bone. "The present findings are not in agreement with a prior study in which tumorigenesis was undertaken using a versican-negative fibrosarcoma cell line and adenovirus Cre-induced stromal Vcan inactivation." (PMID 29222454, 2017).
gastric adenocarcinoma (2 papers, 2015 to 2019). "Together with our studies of gastric adenocarcinoma, these data support the view that Versican mRNA expression levels may be associated with cancer development." (PMID 26619403, 2015). "(Figure-2) Significantly shorter survival was seen among patients whose gastric adenocarcinoma expressed epithelial or stromal versican." (PMID 31531098, 2019). "Shorter survival was observed among patients whose gastric adenocarcinoma expressed epithelial or stromal versican." (PMID 31531098, 2019). "The present study revealed that the expression of versican in the tumor area predicts a poorer prognosis in gastric adenocarcinoma." (PMID 31531098, 2019). "In summary, the present study suggests that versican is likely a prognostic biomarker that predicts a poor out- come in patients with gastric adenocarcinoma." (PMID 31531098, 2019). "The staining of Versican was significantly more intense in gastric adenocarcinoma cases than that in either IN or ANT tissues." (PMID 26619403, 2015). "So we performed quantitative real-time (RT) polymerase chain reaction with RNAs isolated from gastric adenocarcinoma tissues to detect the expression levels of Versican." (PMID 26619403, 2015). "The aim of our study was to investigate Versican expression in gastric adenocarcinoma and to determine its relationship with clinicopathologic factors, with a special emphasis on its prognostic significance." (PMID 26619403, 2015). "Taken together, these data suggested that Versican was highly expressed in gastric adenocarcinoma both on mRNA and protein levels." (PMID 26619403, 2015). "It turned out that Versican expression was significantly greater in tumor tissues compared with adjacent normal tissues (ANTs; P<0.001), suggesting that Versican was highly expressed in malignant gastric adenocarcinoma." (PMID 26619403, 2015). "The aim of our study was to investigate versican expression in gastric adenocarcinoma." (PMID 31531098, 2019). "The first goal of our study was to investigate whether Versican is detectable and altered in gastric adenocarcinoma tissues compared with adjacent normal ones." (PMID 26619403, 2015).
gastric tumors (2 papers, 2019 to 2021). "Most versican expression in epithelial gastric tumor cells was in the body (50.0%) and most of the expression of versican in stromal gastric tumor cell was in the antrum (41.2%)." (PMID 31531098, 2019). "Versican expression was observed in the epithelial and stromal cells of gastric tumors, separately." (PMID 31531098, 2019).
glaucoma (2 papers, 2008 to 2025). Increased pressure in the eyeball due to obstruction of the outflow of aqueous humor. "In the current study, using microarray analysis, we identified a number of genes (for example, MYLK, TGFBR2, VCAN, and RAC2) whose expression may underlie higher susceptibility of astrocytes of AA individuals to elevated IOP and that may be relevant to reactive astrocyte responses in glaucoma." (PMID 18613964, 2008). "Regulation of versican (VCAN) by hsa-miR-218-5p, hsa-miR-101-3p was identified in our results but has not been reported in XFG or other forms of glaucoma to our knowledge." (PMID 39883689, 2025).
glomerulosclerosis (2 papers, 2011 to 2012). A hardening of the kidney glomerulus caused by scarring of the blood vessels. "Although glomerulosclerosis and both versican isoforms also showed significant associations with creatinine at follow-up, the addition of glomerulosclerosis and either V0 or V1 or both isoforms to creatinine did not increase the predictive value of creatinine to a significant extent." (PMID 23024773, 2012). "However, when patients with acute kidney failure at time of biopsy (n = 5) were excluded, the additive predictive value of versican V1 was only marginally higher (35%) than creatinine and glomerulosclerosis alone (34%)." (PMID 23024773, 2012). "Versican isoforms V0 and V1 together with serum creatinine at time of biopsy and the degree of glomerulosclerosis predicted 20% and 24% of the variability of creatinine at follow up, which was significantly more than serum creatinine and histological parameters alone (16%)." (PMID 23024773, 2012).
Hyperglycemia (2 papers, 2019 to 2021). An increased concentration of glucose in the blood. "A recent in vitro study showed that hyperglycemia-induced exosomal vesicles from HUVEC are able to promote calcification in vascular smooth muscle cells via versican activation." (PMID 34222223, 2021). "VCAN participates in hyperglycemia-induced calcification/senescence via modulation of mitochondrial function in VSMCs." (PMID 30622695, 2019).
Insulin resistance (2 papers, 2017 to 2021). Increased resistance towards insulin, that is, diminished effectiveness of insulin in reducing blood glucose levels. "Serum versican levels, homeostasis model assessment of insulin resistance index, a Ferriman-Gallwey score higher than 8, and oligomenorrhea were the strongest predictors of PCOS." (PMID 27908842, 2017). "Furthermore, previous studies suggested a relationship between versican and atherosclerosis, diabetes, insulin resistance (IR) and endothelial dysfunction, which are well-known long-term consequences of PCOS." (PMID 27908842, 2017).
interstitial lung disease (2 papers, 2013 to 2014). A diverse group of lung diseases that affect the lung parenchyma. "Versican overexpression has been poorly studied in interstitial lung diseases, however its effects on motility, invasion and metastasis have been widely reported in cancer." (PMID 25064447, 2014).
liver cancer (2 papers, 2022 to 2023). An epithelial or non-epithelial malignant neoplasm that arises from the liver. "Previous studies showed that some proteoglycans, such as glypicans, agrin, and versican, play a key role in the development of liver cancer, and heparan sulfate proteoglycans were regarded to be the critical targets for the diagnosis and therapy of CRC." (PMID 36624500, 2023). "The immunohistochemical staining results of VCAN protein downloaded from the HPA database indicated moderate staining for VCAN protein in liver cancer, but no detectable expression in the normal liver tissue." (PMID 36275632, 2022).
periodontitis (2 papers, 2022 to 2025). An acute or chronic inflammatory process that affects the tissues that surround and support the teeth. "The upregulation of genes encoding components of the extracellular matrix (ECM) and basement membrane, such as versican (Vcan) and nidogen-1 (Nid1), was also found in gingival tissue with periodontitis." (PMID 40076622, 2025).
pneumonia (2 papers, 2023 to 2025). An acute, acute and chronic, or chronic inflammation focally or diffusely affecting the lung parenchyma, caused by an infection in one or both of the lungs (by bacteria, viruses, fungi, or mycoplasma.). "Among the C-type lectin receptors that respond to respiratory infection, such as versican and surfactant protein D, Mincle (macrophage inducible C-type lectin receptor) has been widely studied and shown to have prominent role against pneumonia." (PMID 36829255, 2023). "In an influenza model of pneumonia, damage-responsive fibroblasts produced the protease ADAMTS4 (a disintegrin and metalloproteinase with thrombospondin motifs 4), leading to the cleavage of versican, enabling immune cell infiltration." (PMID 36829255, 2023).
prostate tumor (2 papers, 2013 to 2022). "According our results, versican was the most stably expressed extracellular proteoglycan in prostate tumours, with the mRNA levels similar to that in normal prostate tissue." (PMID 23691363, 2013). "As a result, expression patterns for main proteoglycans in prostate tumours were highly individual with an ubiquitous expression for versican and tendency for the decreased decorin and lumican expressions and increased syndecan-1 and glypican-1 expressions in tumour tissues." (PMID 23691363, 2013). "Whereas the versican expression level was relatively similar both in normal and malignant prostate tissues (35–40% of increase for versican expression was not considered as significant), decorin and lumican expressions trend towards to be decreased in prostate tumours up to 2-fold." (PMID 23691363, 2013). "In this study, expression of cell surface and stromal proteoglycans (glypican-1, perlecan, syndecan-1, aggrecan, versican, NG2, brevican, decorin, and lumican) in normal tissue and prostate tumours was determined by RT-PCR analysis and immunostaining with core protein- and GAG-specific antibodies." (PMID 23691363, 2013). "Possibly, an accumulation of versican in cancer prostate tissue is due to either posttranscriptional activation of versican expression or decreased versican degradation in prostate tumours but not versican regulation at mRNA level." (PMID 23691363, 2013).
retinal detachment (2 papers, 2020 to 2025). An eye emergency condition which may lead to blindness if left untreated. "As such, deficiencies of versican may predispose to excessive vitreoretinal traction, thereby increasing the risk of retinal detachment in patients with severe ROP." (PMID 40747364, 2025).